AIM2 (absent in melanoma 2)
Diseases named in the same sentence as AIM2 in open-access papers (continued):
Sharing a sentence is not in itself a finding about the gene and the disease.
infection (continued). "CAST/EiJ mice succumbed to high-dose MPXV infection within 8 days, whereas AIM2 inhibition increased survival, with 10% of the mice treated with an AIM2 inhibitor surviving the infection." (PMID 41225161, 2025). "Collectively, during pathogen infection, various cell death-related molecules orchestrate the assembly of AIM2-PANoptosome and promote PANoptosis, thereby eliciting host defense mechanisms." (PMID 41479920, 2025). "On days 1, 2, and 3 post-infection, the mice received intraperitoneal injections of 0.3 mg of AIM2 inhibitor (ODN TTAGGG sodium; MCE, Cat# HY-150751C) diluted in DPBS." (PMID 41225161, 2025). "Fluorescence microscopy was used to assess the transfection efficiency of BV2 cells with various AIM2 shRNA sequences at different multiplicities of infection (MOIs)." (PMID 39969742, 2025). "IL-1β, IL-18, and LDH levels in the BALF 5 days after MPXV infection exhibited an AIM2-dependent effect." (PMID 41225161, 2025). "Emerging data suggest that AIM2, in conjunction with other inflammasome sensors, can be activated in response to live-pathogen infections due to the presence of multiple PAMPs and DAMPs." (PMID 41225161, 2025). "In a low-dose infection model, AIM2 inhibition reduced IL-1β and IL-18 production, LDH release, and tissue pathology." (PMID 41225161, 2025). "Infection of AIM2-knockdown dermal fibroblast with Chikungunya or the West Nile virus led to a decrease in IL-1β production." (PMID 40006996, 2025). "In this study, we employed an intranasal infection model to investigate AIM2-dependent inflammatory responses and the systemic pathogenesis of MPXV." (PMID 41225161, 2025). "To identify the inflammasome sensors responsible for the recognition of A. baumannii, we inoculated WT BMDMs with A. baumannii 1605 and measured Nlrc4, Aim2, Nlrp3 and Caspase-11 transcript levels in cell lysates at 6- and 12-hours post infection." (PMID 39533032, 2024). "This underscores the need for further research to better understand the repertoire of PAMPs/DAMPs that trigger AIM2 during infection." (PMID 39459869, 2024). "To find out how M84 affects AIM2 inflammasome signaling upon infection, we infected J774A.1 macrophages with WT MCMV or the M84stop mutant and analyzed the release of Caspase-1 into the supernatant." (PMID 38278864, 2024). "M. tb has evolved mechanisms to inhibit AIM2 inflammasome activation, allowing it to evade immune detection and establish a persistent infection." (PMID 39125766, 2024). "In order to assess the potential impact of IFN-I on the susceptibility of Aim2−/− mice to C. albicans infection, we conducted an investigation into the gene and protein expression of IFN-I in the kidneys of both WT and Aim2−/− mice following infection." (PMID 38918243, 2024). "Infections caused by ssRNA viruses, Chikungunya (CHIKV), Zika (ZIKV), and West Nile (WNV), have been observed to upregulate AIM2 expression in dermal fibroblasts." (PMID 39459869, 2024). "Infection of Aim2 or Asc knockout iBMDM resulted in very low levels of PI-positive cells, both with WT MCMV and the M84stop mutant." (PMID 38278864, 2024). "This unique structure allows AIM2 to act as a sensor for cytosolic DNA and specifically recognize the DNA released by M. tb during infection." (PMID 39125766, 2024). "Instead, Aim2−/− mice display lower levels of apoptosis in kidney tissues following infection than WT mice." (PMID 38918243, 2024). "In vitro data similarly revealed that depletion of AIM2 or ASC in murine macrophage cell lines diminishes IL-1β release following infection with Mtb or Mycobacterium bovis." (PMID 39324136, 2024). "Unlike NLRP3, which responds to RNA viruses by indirectly detecting viral RNA, cellular stress and damage, AIM2 directly binds to cellular or viral dsDNA released during infection or cell death." (PMID 39459869, 2024).
infection (continued). "We next examined the impact of F. tularensis LVS infection on the cGAS-STING pathway upstream of Aim2 by determining the levels of IFN-β in wild-type, Aim2−/−, Sting−/− and immortalized Gsdmd−/− BMDMs." (PMID 37266012, 2023). "Since MER41.AIM2 was identified as the only STAT1 binding site within 50 kb of the AIM2 gene, it was predictable that AIM2′s upregulation following interferon γ treatment or infection by vaccinia virus was abolished in MER41.AIM2-KO cells." (PMID 36839434, 2023). "Mitochondrial dysfunction exacerbates inflammatory responses to M. tuberculosis, as macrophages with the PD disease mutation Lrrk2G2019S exhibit mitochondrial dysfunction, enhanced mtDNA release, and AIM2 inflammasome activation upon infection." (PMID 37001140, 2023). "Infection with HSV1 or F. novicida can induce AIM2-dependent and NLRP3/NLRC4-independent activation of CASP1, followed by the release of IL-1β and IL-18 and cell death." (PMID 36845112, 2023). "In the host immune response induced by infection, AIM2 can form PANoptosome with ZBP1 and another type of inflammasome Pyrin." (PMID 38203518, 2023). "In EV-A71 infected SK-N-SH and SK-N-SH/si AIM2 cells, the co-localization of virus and AIM2 antigens was found, suggesting AIM2 inflammasome-induced pyroptosis following EV-A71 infection." (PMID 37608944, 2023). "Upon infection, a toxin-dependent induction of Aim2 mRNA was observed in the colon despite similar levels of bacterial recovery in the two infected groups." (PMID 38274797, 2023). "What these bacteria have in common is that the infection processes often involve bacteriolysis to expose bacterial DNA to AIM2." (PMID 37817895, 2023). "Following the induction of infection in J774A.1 by Mtb, silencing of AIM2 restored autophagic flux, with a significant increase in LC3 II and a rapid decrease in p62 protein levels." (PMID 37125940, 2023). "In this review, we will focus on the NLRP3, NLRP6, NLRC4 and AIM2 inflammasomes and how they are activated and regulated during infections with Gram-positive bacteria, including Staphylococcus spp., Streptococcus spp." (PMID 36761775, 2023). "Another cytosolic sensor, AIM2, induces PANoptosis in macrophages upon infection with HSV1 or F. novicida." (PMID 37612410, 2023). "Using these models, they showed that inflammasome pathway components (NLRP3, ASC, AIM2, and caspase-1) are induced upon infection of bone marrow-derived macrophages." (PMID 36298668, 2022). "By knocking down AIM2, the authors showed significantly decreased activation of caspase-1 in response to infection with vaccinia virus." (PMID 36298668, 2022). "DNA viruses and intracellular bacteria release DNA during infection, which activates the AIM2 inflammasome." (PMID 35351143, 2022). "In canonical pathway, inflammasomes such as NLRP3, NLRP4 and AIM2 are responsible for recognizing extracellular pathogens infection and then activate the caspase-1, which cleaves GSDMD into the N-terminus and C-terminus fragments later." (PMID 35573789, 2022). "A recent study showed that AIM2 can amplify signals of infection and trigger atypical NLRP3 activation, and another study showed that the inflammasome adaptor ASC is required for their assembly." (PMID 36151570, 2022). "Activation of AIM2 inflammasome has been reported in several cell types during infection with various mycobacterial species, including Mycobacterium smegmatis (Msme), Mycobacterium fortuitum (Mfor) and Mkan in BMDCs." (PMID 35237260, 2022). "Following analysis of all known PRRs available in the transcriptomic sequencing, Aim2 gene was identified significantly upregulated upon ΔoatA mutant infection." (PMID 36128739, 2022). "Loss of AIM2 reduced the expression of Pyrin and ZBP1 during these infections, indicating that AIM2-mediated signaling functions as an upstream regulator of Pyrin and ZBP1 to control assembly and activation of the AIM2 PANoptosome." (PMID 34471287, 2021).
infection (continued). "Aim2-KO mice succumbed rapidly to infection with one million CFU H37Rv strain delivered i.t. compared to WT." (PMID 34276708, 2021). "Common PRRs of NOD1, NOD2, NLRP3, NLRC4, NLRC5, and AIM2 were detected using qPCR assays after 90 min of infection with A. sobria at a MOI of 10 and 2 h gentamycin treatment followed by 12 h incubation." (PMID 34513725, 2021). "Aim2-/- mice succumb within 7 weeks following intratracheal infection with MTB H37Rv, while WT mice are able to survive at least 8 weeks." (PMID 33503864, 2021). "IFN-I is required for AIM2 inflammasome activation response to F. novicida U112 infection, because the expression of critical host factors involved in intracellular bacteriolysis is dependent on IFN-I signaling." (PMID 34869331, 2021). "The absent in melanoma 2 (AIM2)/ASC inflammasome that recognize double-stranded DNA plays a role in pathogen infection." (PMID 34122076, 2021). "Compared to peritoneal macrophages from WT mice, cleavage of caspase-1 and expression of IL-1β and IL-18 at both the mRNA and protein levels are reduced in the cells from Aim2-/- mice following infection with MTB." (PMID 33503864, 2021). "The transcript levels of DNA sensors Aim2, cGas, and Sting were also significantly elevated in the Nlrp3−/− mice on day 7 post-infection than those observed for F. tularensis LVS-infected wild-type mice." (PMID 34690967, 2021). "F. novicida has served as a prototype for activation of the AIM2 inflammasome and it has been demonstrated that the infection leads to activation of caspase-1 and cleavage of the precursors of IL-1β and IL-18, thereby leading to their secretion." (PMID 35004352, 2021). "NLRP3 and AIM2 are known to play critical roles in inflammasome activation upon a variety of cellular infection or stress." (PMID 34006824, 2021). "AIM2 has been mostly studied in cells of the immune system or within the context of infection; however, its role in other tissues remains to be investigated." (PMID 33162829, 2020). "Recent data have demonstrated that infection by helminths of the Schistosoma genus affects the expression of several nucleic acids sensors, such as AIM2, TLR3, and TLR75,31,32." (PMID 32404867, 2020). "From these analyses, AIM2 rose as a lead PRR candidate for danger-signaling mediator during OAd.TNFa-IL2 infection." (PMID 32225009, 2020). "The residual caspase-1/11, ASC-dependent and NLRP3/AIM2-independent maturation of IL-1β in response to infection with H37Rv and isolate 411 suggests the involvement of an additional inflammasome sensor in detecting these bacteria." (PMID 32111888, 2020). "Despite such evidence, some studies suggest that AIM2 can play a protective role in some infections." (PMID 33042875, 2020). "An important host factor that VP22 interacts with is the AIM2 inflammasome, promoting the evasion of AIM2-dependent inflammasome activation during infection." (PMID 33374862, 2020). "This indicates that in proinflammatory macrophages, IFI16 and AIM2 are dispensable for HSV-1 induced inflammasome activation early during infection." (PMID 32101570, 2020). "We discovered that the McKrae and KOS strains, but not the F strain, induced a significant level of AIM2 in human primary corneal epithelial cells, at 4 and 8 h post-infection, however AIM2 expression faded by 24 h." (PMID 31367214, 2019). "Together, these results indicated that upon infection of HSCs, B. abortus triggers AIM2 and NLRP3 inflammasome activation with concomitant IL-1β secretion in a mechanism that is dependent on a functional T4SS and DNA." (PMID 32038610, 2019). "To further demonstrate the direct involvement of pDCs for early IFN-α and IFN-β production, we depleted pDCs in Aim2−/−, Nlrp3−/−, Casp1−/−, and Il1r1−/− mice by injection of anti-mPDCA-1 antibody at 12 h before and 12 h after infection." (PMID 30470758, 2018).
infection (continued). "In contrast, acute infection of human primary fibroblasts with ZIKV revealed that the virus induces specific activation of inflammasome components such as AIM2 and interleukin-1β (IL-1β)." (PMID 30453621, 2018). "To exclude the possibility that macrophages and cDCs also contribute to early IFN-α and IFN-β production, we also depleted macrophages in Nlrp3−/− or Aim2−/− mice by intraperitoneal injection of clodronate liposome at 2 days before YM infection." (PMID 30470758, 2018). "We observed that pUL83 (green signal) and AIM2 (red signal) co-localized in the cytoplasm at 6 h and 12 h post infection (white arrow), whereas the AIM2 signal weakened at 24 h post infection." (PMID 28219398, 2017). "The double-stranded DNA sensor AIM2 is known to recruit ASC to trigger puncta formation in response to infection, leading to caspase-1 activation and IL-1β and IL-18 release." (PMID 28771586, 2017). "A moderate pUL83-specific band was observed 6 h post infection, and a more distinct band was seen 12 h post infection (IP: AIM2 fraction)." (PMID 28219398, 2017). "Pyroptosis attenuates infection by eliminating the replication niche of L. monocytogenes; as such, cytosolic survival and avoidance of detection by the AIM2 inflammasome are critical for L. monocytogenes pathogenesis." (PMID 28325762, 2017). "The protein level of AIM2, the cytoplasmic sensor molecule, was elevated over time after infection of THP-1 cells despite the fact that AIM2 mRNA increased only at 6 hours post EBV incubation and subsequently decreased." (PMID 28369146, 2017). "For direct destruction of bacteria residing in the cytosol it can be argued that assembly and activation of the AIM2 inflammasome during infection with F. novicida requires transcription factor IRF1." (PMID 29085810, 2017). "Infections with pdhC::Tn and yvcJ::Tn mutants induced significantly higher levels of caspase-1- and AIM2-dependent cell death in macrophages in comparison to wild-type results as expected." (PMID 28325762, 2017). "AIM2-inflammasome signaling during infection by virulent and avirulent mycobacteria and its interaction with IFN-β has been reported, but the findings are not in accord with each other." (PMID 29258190, 2017). "The proposed biological significance of the pUL83/AIM2 interaction should be investigated in depth in an in vivo infection model, by either overexpressing or deleting the UL83 gene." (PMID 28219398, 2017). "In summary, our data suggest that pUL83 interacts with AIM2 in HCMV-infected macrophages at the early infection stage." (PMID 28219398, 2017). "Expression of AIM2 was prominent 6 h and 12 h post infection, but it was only weakly apparent 24 h post infection, comparable with the mock-infected control." (PMID 28219398, 2017). "Taken together, these findings suggest that AIM2 is a common danger sensor in different cell types, which helps the host to be exempt from infection and transformation, and thus maintains the intracellular homeostasis and sanctity." (PMID 27167192, 2016). "Although we do not further pursue the mechanism responsible for increased IL-1β release in Aim2-/- mice following Ft LVS infection in this report, this effect was consistently observed in all our experiments." (PMID 27926940, 2016). "The Aim2 inflammasome response is critical for resistance to intradermal infection with F. novicida." (PMID 27926940, 2016). "The selectivity of the fenamates to NLRP3 over other inflammasomes reported here is another advantage since their use would avoid compromising NLRC4 or AIM2 inflammasome-dependent host responses to infection." (PMID 27509875, 2016). "Curiously, macrophages from Aim2-/- mice produced more IL-1β than wildtype cells in response to LVS infection but IL-1β production following SchuS4 infection was limited." (PMID 27926940, 2016). "NLRP3 protein exhibited an apparent change at 6 and 24 h after B. melitensis 16M infection, while the AIM2 protein underwent a marked change at 6 h." (PMID 27907115, 2016).
infection (continued). "Instead, we observed small, but statistically significant increases in host cell death following infection with strains that activate the AIM2 inflammasome including wild type, holin-lysin and ΔprkA L. monocytogenes." (PMID 27806131, 2016). "The discovery of AIM2 as a novel inflammasome receptor led us to examine its role during infection with F. novicida." (PMID 25879288, 2015). "Infection of murine bone marrow derived macrophages (BMM) with wild-type F. novicida results in activation of the AIM2 inflammasome and pyroptosis, which can be monitored by real time incorporation of the membrane-impermeable dye propidium iodide." (PMID 24453979, 2014). "Activation of inflammasome complexes is a key innate immune response against infection with microbial or viral pathogens and tissue damage, and the AIM2 inflammasome appears to be an important mediator of this process in HBV-GN." (PMID 24701032, 2014). "The sole known inflammasome activated following infection of mouse cells with Fn is the AIM2 inflammasome." (PMID 25191316, 2014). "In order to investigate if this increased type I IFN observed in inflammasome-deficient macrophages was responsible for the faster AIM2/ASC complex formation, we primed macrophages with IFN-β, 3 h before infection." (PMID 23630667, 2013). "ASC, a component of the inflammasome, and AIM2 (which recognizes F. tularensis DNA) are crucial for control of Francisella intra-macrophage growth in vitro and infection in vivo." (PMID 23403609, 2013). "In contrast, IFN-β increases activity of the AIM2-inflammasome after infection with intracellular pathogens such as Francisella tularensis and Listeria monocytogenes." (PMID 24130966, 2013). "More recently, it has been demonstrated that the AIM-2 inflammasome mediates caspase-1 activation and secretion of mature IL-1β and IL-18 during FT infection." (PMID 21819572, 2011). "In addition to its role in bacterial pathogens, AIM2 is also activated during infection with DNA and RNA viruses." (PMID 41062723, 2025). "The importance of the AIM2 inflammasome during infection with DNA viruses is further demonstrated by mechanisms in which viruses directly block AIM2, with the tegument protein pUL83 from human cytomegalovirus and VP22 from herpes simplex virus-1 interacting with and inhibiting AIM2." (PMID 41062723, 2025). "were addressing, whether Mtb could actively inhibit AIM2 inflammasome activation originating from other sources, such as simultaneous infection of BMDMs with Mycobacterium smegmatis." (PMID 39324136, 2024). "Furthermore, to confirm that NLRP3 or AIM2 is important for inflammasome activation during infection with A. actinomycetemcomitans, as reported in previous studies, we used BMDMs from wild-type, NLRP3-deficient, or AIM2-deficient mice." (PMID 39143049, 2024). "Absent in melanoma 2 (AIM2), a pattern recognition receptor for DNA sensing, is well recognized for its involvement in inflammasome formation and its crucial role in safeguarding the host against various pathogenic infections." (PMID 38918243, 2024). "While a transient reduction in IL-1β, IL-6 and tumour necrosis factor (TNF) secretion was observed during acute infection, levels returned back to WT or higher 5 days post-infection (dpi), suggesting ablation of AIM2 may rather facilitate severe inflammation." (PMID 39459869, 2024). "perfringens soft tissue infection, revealing the importance of AIM2 in host protection." (PMID 38928277, 2024). "Additionally, infection of macrophages with F. tularensis generates cytosolic DNA that specifically binds to AIM2, inducing AIM2 oligomerization, which subsequently leads to the activation of caspase-1 and cell death." (PMID 39076969, 2024). "Furthermore, murine BMDMs and human THP-1 macrophages undergo AIM2-dependent PANoptosis during infection with HSV1 or Francisella novicida." (PMID 37612410, 2023).